CEACAM1 (CEA cell adhesion molecule 1)
Diseases named in the same sentence as CEACAM1 in open-access papers (continued):
Sharing a sentence is not in itself a finding about the gene and the disease.
Hepatic steatosis (12 papers, 2015 to 2026). Steatosis is a term used to denote lipid accumulation within hepatocytes. "Mice with a global Ceacam1 null mutation fed a high-fat diet to induce obesity exhibited worsened liver steatosis, increased hepatic inflammation, and stimulated fibrosis in the knockout, but no fibrosis was observed in control mice on the same diet." (PMID 40985048, 2025). "In summary, the current studies demonstrate a strong association between reduced CEACAM1 expression in hepatocytes with obesity, hepatic steatosis, and dyslipidemia across species and multiple rat strains." (PMID 28396653, 2017). "In a cohort of obese South Korean patients, CEACAM1, a major player in promoting insulin clearance, was reported to be progressively reduced with increased hepatic steatosis independently of type 2 diabetes." (PMID 36009446, 2022). "Here, we reported the use of [18F]FTO as a tracer to evaluate cardiac imaging in the Ceacam1−/− animal model that develops fatty liver disease and CVD." (PMID 36559027, 2022). "Taken together, these studies indicate that male Ceacam1−/− mice are a good model for the development of CVD in fatty liver disease, in which fatty acid uptake and metabolic dysfunction are key factors." (PMID 36559027, 2022). "Immunohistological analysis revealed reduction of hepatic CEACAM1 in obese subjects with fatty liver disease." (PMID 28396653, 2017). "Together, this supports an important role for altered CEACAM1-dependent insulin clearance pathways in the pathogenesis of diet-induced hepatic steatosis and visceral obesity." (PMID 26284027, 2015). "This highlights a key role for CEACAM1-dependent insulin clearance pathways in maintaining insulin sensitivity and limiting hepatic steatosis by promoting hepatic insulin clearance and mediating the anti-lipogenic effect of acutely released insulin in hepatocytes." (PMID 39640841, 2024). "In mice, deletion or functional inactivation of CEACAM1 impairs insulin clearance and compromises metabolic homeostasis which initiates the development of obesity and hepatic steatosis and fibrosis with other features of non-alcoholic steatohepatitis, and adipogenesis in white adipose depot." (PMID 30314283, 2018). "Similarly, primary hepatocytes from obese humans and rat models of obesity and hepatic steatosis exhibit a decline in CEACAM1 levels." (PMID 30314283, 2018). "We chose the male Ceacam1−/− model that develops fatty liver disease and CVD in an age related manner on normal chow, since fatty liver disease is known to occur in both obese and nonobese adults, is age related, and has a sex prevalence in males." (PMID 36559027, 2022).
Obesity (12 papers, 2011 to 2026). Accumulation of substantial excess body fat. "That obesity and hepatic steatohepatitis are associated with impaired insulin clearance is demonstrated by the repression of hepatic CEACAM1 expression by high-fat (HF) intake via a peroxisome-proliferator-activated receptor α (PPARα)-dependent mechanism." (PMID 30314283, 2018). "The current studies demonstrate that by comparison to lean controls, CEACAM1 level is reduced in the liver of age- and sex-matched obese human subjects and in three rat models of obesity resulting from null mutation of leptin receptor." (PMID 28396653, 2017). "Increased lipolysis-driven hepatic fatty acid β-oxidation in humans with uncomplicated obesity and its role in regulating hepatic de novo lipogenesis propose an important role for the loss of hepatic CEACAM1 in the regulation of lipid homeostasis in hepatocytes derived from obese humans." (PMID 28396653, 2017). "In metabolic regulation, deletion or inactivation of CEACAM1 impairs insulin clearance in mice, compromising metabolic homeostasis and promoting obesity, hepatic steatosis, and fibrosis." (PMID 36741860, 2023). "This study supports that a decreased CEACAM1 expression in liver is related to obesity and a fatty liver." (PMID 21569294, 2011). "It has been shown that obesity decreases CEACAM1 and IDE expression." (PMID 36675244, 2023). "Furthermore, global Ceacam1 null mice develop leptin resistance, which contributes to hyperphagia, fat accumulation, and reduction of physical inactivity; all leading to obesity." (PMID 30314283, 2018). "To investigate whether the reduction in hepatic CEACAM1 in obesity is common among species, we then examined mRNA levels of Ceacam1 in the livers of obese male rats." (PMID 28396653, 2017). "A decreased CEACAM1 expression was also associated with severe obesity with or without diabetes rather than being associated with non-obesity with or without diabetes (p < 0.05)." (PMID 21569294, 2011). "The aim of this study is to evaluate the expression of CEACAM1 in the human liver tissue of diabetics and non-diabetics who are with or without severe obesity." (PMID 21569294, 2011). "The incidence of a decreased CEACAM1 expression was significantly higher in high grade fatty liver as well as severe obesity with or without diabetes (p < 0.05)." (PMID 21569294, 2011). "In humans, decreased liver CEACAM1 expression is significantly more prevalent in individuals with MASLD and severe obesity, regardless of their diabetic status." (PMID 40985048, 2025).
non-small cell lung carcinoma (11 papers, 2010 to 2024). A group of at least three distinct histological types of lung cancer, including non-small cell squamous cell carcinoma, adenocarcinoma, and large cell carcinoma. "For example, studies on oral squamous cell carcinoma and non-small cell lung cancers showed that CEACAM1 overexpression were associated with angiogenesis." (PMID 24587171, 2014). "CD44 variant, NM_001001390 and CEACAM1 variant, NM_000610 are found to be linked to NM_201283 of EGFR, in cancer samples and are also in reported to be critical in non-small cell lung cancers." (PMID 25034693, 2014). "Zhou’s group reported that CEACAM1 expression was significantly increased in early stage non-small-cell lung cancer (NSCLC) patients indicating that CEACAM1 could be used for early diagnosis." (PMID 27074014, 2016).
pancreatic cancer (11 papers, 2010 to 2023). "According to the literatures, the diagnostic efficiency of serum CEACAM1 varied among cancers, but as a single diagnostic biomarker, high AUCs for serum CEACAM1 were noted in pancreatic cancer and NSCLC patients (AUCs of 0.936 and 0.96, respectively)." (PMID 27074014, 2016). "Overexpression of other CEACAMs (CEACAM1, 5, 6) was a predisposition factor for pancreatic cancer." (PMID 32899471, 2020). "In another study, CEACAM1 was shown to be upregulated in 69% of pancreatic carcinomas compared to 2% in normal patients, and patients with low serum CEACAM1 levels have significantly increased rates of overall survival." (PMID 36741860, 2023). "Simeone’s group reported the potential of CEACAM1 as a serum tumor biomarker in pancreatic carcinoma and noted significantly elevated CEACAM1 had comparable specificity and sensitivity to CA19-9, a current standard serum biomarker for pancreatic cancer." (PMID 27074014, 2016). "CEACAM-1 was shown to be overexpressed in colon, breast, lung, and pancreatic cancer." (PMID 34830745, 2021). "The serum of CEACAM-1 served as a useful indicator for the presence of pancreatic cancer." (PMID 29122006, 2017). "Also, the combination of CEACAM1 and CA19-9 had significantly higher diagnostic accuracy for pancreatic cancer than using either marker alone." (PMID 27074014, 2016). "A clinical study found that CEACAM1 was expressed in the sera of 24% (15/61) of normal patients, 66% (35/53) of patients with chronic pancreatitis, and 91% (74/81) of pancreatic cancer patients, indicating that CEACAM1 may be a viable biomarker for pancreatic cancer." (PMID 36741860, 2023). "Although CEACAM1 was not proven highly expressed in the high mRNAsi score group, or closely correlated with ICS and MTS, it can be inferred that CEACAM1+ CEACAM5+ cancer cells may be a small subpopulation of CEACAM5+ pancreatic cancer stem cells endowed with an elevated immune privilege." (PMID 36494785, 2022). "A three-marker panel of Ca19–9, CEACAM-1, and MIA differentiated patients with pancreatic cancer from benign pancreatic conditions such as CP, with an AUC of 0.86." (PMID 34830745, 2021). "In pancreatic cancer, the transition between IOIPMN to IPMC includes the following genes: FAR1, CEACAM1, HCCS." (PMID 33265245, 2018).
Sepsis (11 papers, 2013 to 2025). Sepsis is defined as life-threatening organ dysfunction caused by a dysregulated host response to infection. "Here, we show that the bacterial R28 protein, which is epidemiologically associated with outbreaks of puerperal sepsis, specifically targets the human receptor CEACAM1." (PMID 37080973, 2023). "Increased T-cell CEACAM1 expression and increased circulating soluble CEACAM1 may contribute to sepsis-associated immune suppression." (PMID 23894299, 2013). "It will be valuable to determine whether sepsis causes a relative or absolute increase in CEACAM1 expressing CD4+ T-cells in future studies." (PMID 23894299, 2013). "In our model, four genes (NR3C2, CEACAM1, VNN1, and SLC2A3) were linked to the development of AKI in patients with sepsis." (PMID 40765579, 2025). "Here, we show that R28, which possesses an IgI3 domain, specifically targets CEACAM1 of human origin to promote events that would collectively favor the development of puerperal sepsis." (PMID 37080973, 2023). "Carriage of spr28 gene, surface expression of the R28 protein and ability to bind CEACAM1 was evaluated for a large collection of strains belonging to emm28, emm2, or emm77 lineages, which included puerperal sepsis isolates." (PMID 37080973, 2023). "The “Sepsis Metascore” subpanel on another hand, consists of a sepsis-specific transcripts including CEACAM1, C3AR1, GNA15, and HLA-DPB1 which have previously been linked to sepsis." (PMID 35186993, 2022). "The percentage CEACAM1 positive CD4+ T-cells in the late-onset sepsis group were higher than in the VLBW infant control group (26.8% ± 24.0 versus 12.0% ± 13.0; P=0.046)." (PMID 23894299, 2013). "The peak CRP level 70 mg/L ± 63 as a measure of acute phase response and inflammation showed a moderate but significant correlation with percentage CEACAM1 positive CD4+ T-cells in sepsis patients (R=0.553, P =0.031)." (PMID 23894299, 2013). "We are the first to demonstrate an increase in CEACAM1 positive CD4+ T-cells in peripheral blood in vivo in humans in sepsis." (PMID 23894299, 2013). "In our AKI cohort, downregulation of CEACAM1 may reflect impaired immune responses in the context of sepsis, leading to the development of SA-AKI." (PMID 40765579, 2025). "A better understanding of the intracellular signaling events affected by R28 engagement of CEACAM1 on neutrophils could help to understand the progression of invasive infections and puerperal sepsis." (PMID 37080973, 2023). "The qPCR results suggest that GK and PFKFB3 might contribute to the progression of S. aureus-induced sepsis, and CEACAM1, TNFAIP6, PSTPIP2, SOCS3, and IL18RAP might be closely linked with E. coli-induced sepsis." (PMID 31093495, 2019). "The qPCR results suggested that GK and PFKFB3 might contribute to the progression of S. aureus-induced sepsis, and GK, CEACAM1, TNFAIP6, PSTPIP2, SOCS3, and IL18RAP might be closely linked with E. coli-induced sepsis." (PMID 31093495, 2019). "Interestingly, in genetically engineered mice that are resistant to apoptosis due to transfection with the anti-apoptosis gene Bcl-2, sepsis results in uniquely decreased transcription of CEACAM1 in splenocytes and increased sepsis survival." (PMID 23894299, 2013). "Further determination of the functional role of CEACAM1 in sepsis seems justified, as targeting CEACAM1 might be of potential therapeutic benefit in sepsis." (PMID 23894299, 2013). "Soluble CEACAM1 levels were persistently elevated at day 7-8 (50.2 ng/mL ± 12.9; P < 0.05), but had returned to normal values in convalescent serum samples drawn 3 months after sepsis onset (15.7 ng/mL ± 12.3)." (PMID 23894299, 2013). "Soluble CEACAM1 may function as a ligand for CEACAM1 and thus altered concentrations of soluble CEACAM1 in sepsis may further influence T-cell functions." (PMID 23894299, 2013).
Sepsis (continued). "Moreover, in sepsis, the interactions of TIM-3 with its ligands, such as Galectin-9, HMGB1, or CEACAM1, may play a crucial role in modulating immune responses and influencing the outcome of sepsis." (PMID 38576606, 2024). "CEACAM1 is also reported to inhibit Toll-like Receptor-2 signaling and Toll-like Receptor-4, thus increased circulating soluble CEACAM1 might contribute to inhibition of Toll-like Receptor responses in sepsis." (PMID 23894299, 2013). "Whether a decrease in splenocyte CEACAM1 expression improves sepsis survival, or whether there is no causal relation, is unknown." (PMID 23894299, 2013). "Furthermore CEACAM1 is also expressed on innate immune cells, such as neutrophils, monocytes, and natutal killer cells, and altered soluble CEACAM1 concentrations in sepsis may directly influence neutrophil and monocyte survival." (PMID 23894299, 2013). "Through searching the sepsis-related publication of the key genes, CCR7, CXCR3, FYN, CEACAM1, CD81, AMPH, HLA-DMA, and G protein-coupled receptors (GPR18) were considered to be key genes." (PMID 34484417, 2021). "Since CEACAM1 generally functions as an inhibitor of T-cell receptor activation, increased CD4+ T-cells CEACAM1 expression in sepsis may contribute to the suppression of T cell functions as observed in sepsis." (PMID 23894299, 2013). "The percentage CEACAM1 positive CD4+ T-cells in VLBW infants was not related to gestational age, antenatal steroids, and time of sampling after sepsis onset." (PMID 23894299, 2013).
bladder cancer (10 papers, 2006 to 2024). "Accordingly, supernatants from the CEACAM1‐overexpressing bladder cancer cell lines inhibited the formation of endovascular and enhance the morphogenesis of VEGF." (PMID 34105305, 2021). "After performing western blot analysis on urinary samples from 135 subjects (93 with UCB and 42 with no UCB), they concluded that urinary bladder carcinoma and an invasive stage are associated with higher urinary levels of CEACAM1." (PMID 30406153, 2018). "Thus, CEACAM1 expression appears to be downregulated in bladder cancer cells, while concurrently upregulated in endothelial cells of tumoral adjacent blood vessels." (PMID 30406153, 2018). "The human carcinoembryonic antigen-related cell adhesion molecule 1 (CEACAM1, also known as biliary glycoprotein or CD66a), can induce angiogenesis via increased expression of VEGF-C in bladder cancer cells." (PMID 23344023, 2012). "CEACAM1 also appears to be a promising endothelial target for bladder cancer therapy; this molecule is involved in the switch from noninvasive and nonvascularized to invasive and vascularized bladder cancer." (PMID 16504122, 2006).
glioma (8 papers, 2015 to 2025). A benign or malignant brain and spinal cord tumor that arises from glial cells (astrocytes, oligodendrocytes, ependymal cells). "Preliminary studies showed the abnormal expression of carcinoembryonic antigen cell adhesion molecule 1 (CEACAM1) in glioma tissues, which was closely associated with multiple clinicopathological factors of patients with glioma." (PMID 36928507, 2023). "Preliminary studies have also shown the abnormal expression of the immune checkpoint molecule CEACAM1 in T-cells of patients with glioma, which was closely associated with clinical factors, including the pathological grading of tumours, patient functional status, and the level of cytokines." (PMID 36928507, 2023). "A recent study combining radiotherapy with CEACAM1 inhibitors resulted in strong and enduring immune responses against murine glioma, leading to extended survival in some mice." (PMID 39949745, 2025). "Immunohistochemistry revealed that the expression of CEACAM1 in murine glioma tissues after radiotherapy was elevated in a time-dependent manner." (PMID 36928507, 2023). "We found that the expression of CEACAM1 was mostly localized on the cell membrane and in some cases in the cytoplasm of glioma cells." (PMID 36928507, 2023). "The expression of CEACAM1 on T-cells in the peripheral blood of patients with glioma was increased after radiotherapy." (PMID 36928507, 2023). "To explore the prognostic prediction value of CEACAM1 in patients with glioma, we conducted Kaplan-­Meier and Cox proportional hazard model analyses based on the CGGA and TCGA databases." (PMID 36928507, 2023). "We aimed to observe the effect of radiotherapy on the expression of immune checkpoint molecule CEACAM1 in patients with glioma and the therapeutical effect of radiotherapy combined with blockade of CEACAM1 in mice with intracranial gliomas." (PMID 36928507, 2023). "Radiotherapy combined with CEACAM1 inhibitors resulted in strong and durable anti-tumour immune responses against murine glioma and long-term survival of some mice." (PMID 36928507, 2023). "Patients with glioma with high galectin 9, PtdSer, and CEACAM1 expression have significantly lower survival rates than patients with low expression of these ligands." (PMID 33800561, 2021). "Overall, these results show that gliomas with higher malignancy are enriched for CEACAM1." (PMID 36928507, 2023). "Using the Chinese Glioma Genome Atlas (CGGA) and The Cancer Genome Atlas (TCGA), we analyzed the CEACAM1 expression profile in different gliomas and further explored the correlation between CEACAM1 expression and clinicopathological characteristics and survival in patients with glioma." (PMID 36928507, 2023). "Up to the present, there are only a few comprehensive reports on CEACAM1 in patients with glioma." (PMID 36928507, 2023). "Thus, in this study, we first observed the expression of CEACAM1 on T-lymphocytes in the peripheral blood of patients with glioma before and after radiotherapy and found that the CEACAM1 expression level was significantly elevated after radiotherapy." (PMID 36928507, 2023). "Silencing CEACAM1 by siRNA can inhibit the invasion and migration of glioma, which suggests that inhibition of CEACAM1 could suppress tumor progression." (PMID 36712923, 2023). "Therefore, we further investigated the therapeutic effect of radiotherapy combined with targeted blockade of CEACAM1 on murine glioma." (PMID 36928507, 2023). "In the present work, most of these exhaustion markers [TIGIT, CEACAM1, CTLA4, LAG3, PD-1, PD-L1, and TIM3] were highly expressed in the high-risk subtype, indicating an elevated level of immune exhaustion in the tumors of high-risk glioma patients." (PMID 34778248, 2021). "Consequently, targeting CEACAM1 could offer an effective immunotherapy strategy for the treatment of glioma." (PMID 39949745, 2025). "Moreover, CEACAM1 was highly enriched in IDH-wildtype gliomas and higher-­grade gliomas." (PMID 36928507, 2023).
glioma (continued). "The expression of CEACAM1 on CD4+ and CD8+ T-cells in the peripheral blood of patients with glioma was significantly higher 1 week after radiotherapy than before radiotherapy and was further increased 1 month after radiotherapy." (PMID 36928507, 2023). "This study aimed to investigate the expression of CEACAM1 on CD4+ and CD8+ T-cells in the peripheral blood of patients with glioma before and after radiotherapy." (PMID 36928507, 2023). "To determine the expression pattern of the TIM3 ligands, galectin 9, PtdSer, CEACAM1, and HMGB1 in gliomas, we examined the RNA-sequencing data of gliomas from GlioVis data portal for the visualization and analysis of brain tumor expression datasets." (PMID 33800561, 2021). "Compared to WHO grade II and grade III glioma, GBM (grade IV) had the highest galectin 9, PtdSer and CEACAM1 expression." (PMID 33800561, 2021).